TIMP1 (TIMP metallopeptidase inhibitor 1)
Diseases named in the same sentence as TIMP1 in open-access papers (continued):
Sharing a sentence is not in itself a finding about the gene and the disease.
gastric cancer (54 papers, 1997 to 2026). A primary or metastatic malignant neoplasm involving the stomach. "Increased levels of TIMP-1 have been found to be associated with poor prognosis in gastric cancer, which relates to the role of matrix metalloproteinases in degrading the ECM." (PMID 35994501, 2022). "We studied the genotype distribution and allele frequencies of SNPs of MMP-2, -7, -8 and -9 and TIMP-1 and -2 in gastric cancer patients in relation to tumour progression, patient survival and tissue antigen expression." (PMID 16940985, 2006). "But, it has been reported that tissue TIMP-1 concentration in gastric cancer was associated with various pathological factors, and patients with high tissue TIMP-1 concentration had poor prognosis in comparison to those with low TIMP-1 level." (PMID 14960203, 2004). "Similarly, expression profiling of TIMP-1 in gastric cancer showed TIMP-1 expressing cells to be mainly tumor-associated myofibroblasts." (PMID 29393911, 2018). "In the present study, we determined the genotype distribution and allele frequencies of SNPs of MMP-2, -7, -8 and -9, and of TIMP-1 and -2 in a cohort of 79 Caucasian gastric carcinoma patients, in which we previously assessed clinical relevance of the respective protein levels." (PMID 16940985, 2006). "Hub genes containing COL5A2, JAG1, TIMP1, FGFR1, PDFGA, VEGFA, and PTK2 were collected from the gene sets and were proven to be linked to the occurrence and development of gastric cancer." (PMID 35875363, 2022). "Immunochemistry revealed that, compared with control colon tissues TIMP1 was upregulated in gastric cancer tissues." (PMID 34775375, 2021). "Studies had shown that TIMP1 was overexpressed and promoted cell proliferation in patients with gastric cancer through the NF-κB-dependent mechanism." (PMID 33015179, 2020). "TIMP1 has been reported to be overexpressed in gastric cancer cells and in the inflammatory cells of the stromal element of the tumor, and high levels of this protein are associated with poor outcome." (PMID 29484116, 2018). "The aim of this study is to determine the role of serum CK18, MMP-9, and TIMP1 levels in predicting R0 resection in patients with gastric cancer." (PMID 29651326, 2018). "We herein identified a large number of genes associated with the ECM and cell adhesion to be differentially expressed in intestinal gastric cancer, including TIMP1, MMP7, FN1, SPARC, LUM and BGN, which were upregulated." (PMID 29484116, 2018). "In our study, serum ICAM-1 and TIMP-1 levels in MNNG-induced gastric cancer were higher than the normal group." (PMID 28119756, 2016). "The higher expression of TIMP1 was detected in 19 of 107 (17.8%) healthy volunteers and in 100 of 112 (89.3%) patients with gastric cancer (χ2 = 112.8, P = 0.0001)." (PMID 23548070, 2013). "For one example, Runx3 has been shown to suppress gastric cancer metastasis through the inactivation of MMP-9 by the upregulation of TIMP-1." (PMID 21904555, 2011). "As in our study, TIMP1 levels have been found to be elevated in gastric cancer patients compared to healthy controls." (PMID 21092330, 2010). "The pre- and post-operative paired plasma samples from gastric cancer patients who underwent radical surgery showed concordant drop for most of the proteins studied, except TIMP1, MIP-1δ and Adipsin." (PMID 21092330, 2010). "This study identifies the SOX9/TIMP1 axis as a key regulator of immune evasion in gastric cancer." (PMID 41270217, 2026). "In early gastric cancer, CAFs may secrete TIMP1 to inhibit matrix metalloproteinases (MMPs) and delay tumor invasion." (PMID 40485724, 2025). "Furthermore, the authors suggest that chemerin promotes gastric cancer cell invasion partly by suppressing Tissue Inhibitors of Metalloproteinases TIMP-1 and TIMP-2." (PMID 39590835, 2024).
gastric cancer (continued). "Although our results suggested that expression of MMP-7 or TIMP-1 alone cannot serve as an indicator for patient prognosis, there was a significant association between coexpression of MMP-7 and TIMP-1 with poor survival of patients with gastric carcinoma." (PMID 33005257, 2020). "TIMP1, serve as a hub gene of gastric cancer, may be a potential prognostic biomarker for gastric cancer." (PMID 31772671, 2019). "The expression level of TIMP1 was significantly increased in the blood of patients with gastric cancer and familial pancreatic cancer, which could make it as a potential serum marker." (PMID 27644693, 2016). "However, the significance of the expression of TIMP-1 in human gastric carcinoma tissue has yet to be clarified." (PMID 9275032, 1997). "However, little is known about the biological role of TIMP1 in gastric cancer." (PMID 34775375, 2021). "Interestingly, MMP9 mainly promotes tumor invasion and metastasis, while TIMP-1 inhibits the functions of MMP9 in gastric cancer, which suggests that the imbalance between MMP9 and TIMP-1 expression may occur in tumor progression." (PMID 31816819, 2019). "Because some gene polymorphisms of MMPs and TIMPs have been found to be related to disease susceptibility and changed gene transcription in vitro, we investigated whether gastric cancer is associated with SNPs of MMP-2, -7, -8 and -9, or their inhibitors TIMP-1 and TIMP-2." (PMID 16940985, 2006). "CXCR4, SPP1, CXCL1, MMP9, and TIMP1 were up-regulated and NFE2L2 was down-regulated in gastric cancer cell lines compared with control." (PMID 38221932, 2024). "The potential of andrographolide lies in its ability to impede the progression of gastric cancer by suppressing MMP-2 and MMP-9 activities simultaneously enhancing TIMP-1 and TIMP-2 expression." (PMID 39583105, 2024). "RA reduces the levels of MMP-9 in gastric cancer cells and has a dual effect on TIMP-1 (Tissue Inhibitor of Metalloproteinase-1), i.e., it inhibits TIMP-1 at the protein level but stimulates its expression at the mRNA level." (PMID 37836581, 2023). "To investigate whether TIMP1 is upregulated in Gastric Cancer (GC), we first examined TIMP1 expression in 42 cases of GC and 42 adjacent normal gastric tissues." (PMID 34775375, 2021). "CD63 positivity in gastric cancer cells or gastric cancer stromal cells is significantly correlated with lymph node metastasis, so it is inferred that CD63-positive exosomes of gastric cancer might also be associated with metastatic niche formation, probably by binding with and inhibiting TIMP1." (PMID 34109113, 2021). "In gastric cancer tissues where protein expression was detected, the levels of the protein (BGN, VCAN, COL1A1 and TIMP1) were higher than in normal tissues." (PMID 34356118, 2021). "The results showed that FN1, TIMP1, SPP1, APOE, and VCAN were related to OS in gastric cancer patients (p < 0.01)." (PMID 33015179, 2020). "Our results showed that the abnormal expression of FN1, TIMP1, SPP1, APOE, and VCAN influenced the prognosis of patients with gastric cancer." (PMID 33015179, 2020). "Here, TSLL successfully suppressed the migration and invasion of gastric carcinoma cells by decreasing the expression of MMP-2 and elevating the expression of TIMP-1." (PMID 32368309, 2020). "The data suggest a role for chemerin in promoting the invasion of gastric cancer cells via CMKLR1 and GPR1at least partly by reducing TIMP1 and TIMP2 expression." (PMID 30719206, 2019). "Ideally, we should evaluate the gene only after determining the roles of MMPs’ inhibitors, such as TIMP-1, TIMP-2, TIMP-3, and TIMP-4, in the development of gastric cancer." (PMID 29228747, 2017). "Tissue inhibitor of matrix metalloproteinase-1 (TIMP-1) is overexpressed in gastric cancer, and the level of TIMP-1 in serum was considered as a marker for prognosis in gastric cancer patients." (PMID 28119756, 2016).
gastric cancer (continued). "Comparing with the normal group, the signal densities of cytokines were upregulated in the MNNG-induced gastric cancer groups, including Activin A, Agrin, IL-1α (both P < 0.01), ICAM-1 (P < 0.001), and TIMP-1 (P < 0.05)." (PMID 28119756, 2016). "Real-Time PCR and western blot showed increasing of HIF-1α in mRNA and protein levels as well as TIMP1, TFF3 in mRNA levels in gastric cancer tissues." (PMID 24927122, 2014). "We examined preoperative kinesin II-associated protein (KAP1), TIMP metallopeptidase inhibitor 1 (TIMP1) and stanniocalcin 2 (STC2) expression levels in patients with gastric cancers to assess their clinical application for diagnosing and monitoring diseases." (PMID 23548070, 2013). "In this study, we detected the expression of KAP1, TIMP1, STC2, TLN2, SRPX2, integrin beta 1 (ITGB1) and SPARC mRNAs in peripheral blood samples from pre-operative gastric cancer patients, patients with recurrence, and healthy volunteers." (PMID 23548070, 2013). "In conclusion, the NF-κB p65 inhibitor, SN50, inhibited the invasiveness of the gastric cancer cells by downregulating the protein expression of MMP-9, PCNA and VEGF and upregulating the protein expression of TIMP-1." (PMID 24137341, 2013). "Expression levels of KAP1, TIMP1 and STC2 are potentially useful as clinical biomarkers for the screening, diagnosis, prognostic and surveillance of gastric cancer." (PMID 23548070, 2013). "KAP1, TIMP1 and STC2 appear to have a role in the progression to metastatic disease in gastric cancer." (PMID 23548070, 2013). "In this study, we detected the expression levels of KAP1, TIMP1, STC2, TLN2, SRPX2 and SPARC mRNAs in peripheral blood samples from pre-operative gastric cancer patients, those with recurrence, and in healthy volunteers." (PMID 23548070, 2013). "High TIMP1 and STC2 expression levels were suspected to be poor prognostic factors of disease recurrence in patients with gastric cancer." (PMID 23548070, 2013). "To corroborate these observations, we now assessed MMP-2 and MMP-9 with new techniques in an expanded group of gastric cancer patients (n=81) and included for comparison MMP-7, MMP-8 and the tissue inhibitors of MMPs, TIMP-1 and -2." (PMID 16538217, 2006). "Furthermore, five of them (FN1, TIMP1, SPP1, APOE, and VCAN) were found to be related to gastric cancer." (PMID 33015179, 2020). "Data also showed that high expressions of fibronectin 1 (FN1), the tissue inhibitor of metalloproteinases 1 (TIMP1), secreted phosphoprotein 1 (SPP1), apolipoprotein E (APOE), and versican (VCAN) were related to a poor overall survival in gastric cancer patients." (PMID 33015179, 2020). "The area under the ROC curves (AUC) of KAP1 was 0.803 ± 0.040 (P = 0.0001), the AUC of TIMP1 was 0.767 ± 0.043 (P = 0.0001) and the AUC of STC2 was 0.769 ± 0.045 (P = 0.0001), thus differentiating preoperative gastric cancer patients from healthy volunteers by ROC curve analysis." (PMID 23548070, 2013). "KAP1, TIMP1 and STC2 expression levels may be potential biomarkers for the screening, diagnosis, prognosis and surveillance of gastric cancer." (PMID 23548070, 2013). "To figure out the possible mechanisms of how IGFBP3 regulate the invasiveness of gastric cancer cells, we examined the mRNA levels of MMP2/MMP7/MMP9/MMP14, TIMP1/TIMP2, uPA and its receptor uPAR, all of which are invasion-related factors, especially in gastric cancer." (PMID 24386080, 2013). "In particular, high TIMP1 and STC2 expression levels could be poor prognostic factors of disease recurrence in patients with gastric cancer." (PMID 23548070, 2013). "Therefore, we examined the effect of coronin 3 knockdown or up-regulation on the expression of MMP-9, cathepsin K (based on the results of the PCR array), MMP-2, TIMP-1 and TIMP-2 in gastric cancer after infection." (PMID 22974233, 2012).
gastric cancer (continued). "IL8, CXCL9/MIG, CCL3/MIP-1α, CCL20/MIP-3α, PDGFR-B and TIMP1 plasma levels were significantly different between the non-malignant group and the gastric cancer group." (PMID 21092330, 2010). "Additionally, TIMP1 is correlated with angiogenesis in CRC, gastric cancer, and CRC metastasis." (PMID 38962272, 2024). "The study showed that KAP1, TIMP1 and STC2 expression levels could differentiate preoperative gastric cancer patients from healthy volunteers, and that TIMP1 and STC2 could differentiate preoperative gastric cancer patients with recurrence from healthy volunteers." (PMID 23548070, 2013). "In addition, median plasma levels of IL8, CXCL9/MIG, CCL3/MIP-1α, CCL20/MIP-3α, PDGFR-B and TIMP1 proteins were significantly different between the non-malignant group and the gastric cancer group." (PMID 21092330, 2010). "Our results showed that although expression of MMP-7 or TIMP-1 alone may not serve as an indicator for patient prognosis, there was a significant association between concomitant positive expression of MMP-7 and TIMP-1 with poor survival of patients with gastric carcinoma." (PMID 33005257, 2020). "The value of MMP-2 as an independent prognostic marker for gastric carcinomas is underscored by our observation that MMP-9, MMP-7, MMP-8, TIMP-1 and TIMP-2 have no prognostic relevance." (PMID 16538217, 2006). "CCL20/MIP-3α, TIMP1, IL8, PDGFR-B, CCL3/MIP-1α and CXCL9/MIG were significantly elevated in the plasma from the gastric cancer patients compared to the plasma from individuals with no visible upper gastro-intestinal pathology or those with benign lesions in stomach." (PMID 21092330, 2010). "In addition, we have shown some of the proteins (CCL20/MIP-3α, TIMP1, IL8, PDGFR-B, CCL3/MIP-1α and CXCL9/MIG) to be detected at a higher level in the plasma from gastric cancer patients than in patients with non-malignant gastric conditions or with normal gastric mucosa." (PMID 21092330, 2010).
prostate carcinoma (54 papers, 1994 to 2026). A carcinoma that arises from epithelial cells of the prostate gland. "PMEPA1 is a gene associated with prostate cancer and other types of cancer, while TIMP1 encodes a metalloproteinase inhibitor." (PMID 40244296, 2025). "In the context of prostate cancer, loss of tissue inhibitor of metalloproteinases-1 (TIMP1) causes activation of MMPs and thereby reprogramming of the SASP into a SASP that fosters metastasis." (PMID 36980745, 2023). "Elevated plasma levels of TIMP-1 are associated with worse clinical outcomes of colon or prostate cancer patients." (PMID 25296976, 2014). "Furthermore, in a preclinical model of prostate cancer, TIMP1 loss, a pan‐matrix metalloproteinase inhibitor, was reported to promote metastasis in senescent tumours." (PMID 34137158, 2021). "Consistently, WPE1-NB26-65, a malignant cell line derived from immortalized prostate epithelial cell line RWPE-1, expressed approximately 10 times more TIMP-1 than its parental cell line, indicating that increased TIMP-1 expression is associated with prostate cancer progression." (PMID 24143225, 2013). "TSP-1 was positively associated with TIMP-1 in a prostate cancer cell line (PC-3)." (PMID 23749112, 2013). "This suggests that TIMP-1 is associated with aggressive behaviour in prostate carcinomas." (PMID 20160732, 2010). "TIMP1 is a crucial molecule in determining the senescence effect in prostate cancer; inactivation of TIMP1 promotes tumor metastasis by activating matrix metalloproteinases, leading to the upregulation of pro-cancer secretory factors." (PMID 39963130, 2025). "Tissue inhibitor of metalloproteinases 1 (TIMP1) has become a marker of prognosis and indicator for checking the clinical response in cancer treatment because TIMP1 is elevated in breast, colon, and prostate cancer patient plasma." (PMID 35399006, 2022). "This study aimed to evaluate the application of MMP-9 and its regulators (TIMP-1, RECK, and miR-338-3p) as diagnostic and prognostic indicators of prostate cancer." (PMID 35097136, 2021). "We designed different CRISPR transcriptional regulatory systems to silence ITGB5 in prostate cancer cells and activate TIMP1 and TMEM176B at the same time." (PMID 34109215, 2021). "The balance between MMP-9 and TIMP-1 are reported to play a critical role of migration and invasion by stimulating degradation of the ECM in prostate cancer cell and is associated with enhanced tumor metastatic potential." (PMID 28108731, 2017). "Recently, some results have provided new evidence that the imbalance of MMP-9/TIMP-1 is one of the regulation mechanisms to promote tumourigenicity and metastasis of prostate cancer cells." (PMID 29228747, 2017). "We found that the inhibition of TIMP-1 activity markedly suppressed tumor growth in mice, consistent with observations in mouse models of prostate cancer." (PMID 27130446, 2016). "The increased expression of v5-epitope tagged TIMP-1 was validated by Western blot analyses of cell culture supernatants of the pooled populations of transduced prostate cancer cells." (PMID 24143225, 2013). "To further assess localization of TIMP-1 in human prostate cancers and determine the potential source(s) of the elevated plasma TIMP-1, we performed immunohistochemistry (IHC) on a panel of human prostate cancer samples and normal prostate tissues." (PMID 24143225, 2013). "The results showed that TIMP-1 protein is up regulated mainly in prostate cancer stroma compared to its normal counterpart." (PMID 24143225, 2013). "To assess how increased expression of TIMP-1 affects prostate cancer cell proliferation in vivo, we performed immunohistochemical analysis of Ki67, a proliferation marker, on the tumor sections." (PMID 24143225, 2013). "Collectively these results demonstrate that 3-azidoWA inhibited the Akt and ERK phosphorylation in cervical and prostate cancer cells and augmented TIMP-1 expression." (PMID 22962598, 2012).